CHMP1B (charged multivesicular body protein 1B)
Description:
Probable peripherally associated component of the endosomal sorting required for transport complex III (ESCRT-III) which is involved in multivesicular bodies (MVBs) formation and sorting of endosomal cargo proteins into MVBs. MVBs contain intraluminal vesicles (ILVs) that are generated by invagination and scission from the limiting membrane of the endosome and mostly are delivered to lysosomes enabling degradation of membrane proteins, such as stimulated growth factor receptors, lysosomal enzymes and lipids. The MVB pathway appears to require the sequential function of ESCRT-O, -I,-II and -III complexes. ESCRT-III proteins mostly dissociate from the invaginating membrane before the ILV is released. The ESCRT machinery also functions in topologically equivalent membrane fission events, such as the terminal stages of cytokinesis and the budding of enveloped viruses (HIV-1 and other lentiviruses). ESCRT-III proteins are believed to mediate the necessary vesicle extrusion and/or membrane fission activities, possibly in conjunction with the AAA ATPase VPS4. Involved in cytokinesis. Involved in recruiting VPS4A and/or VPS4B and SPAST to the midbody of dividing cells. Involved in HIV-1 p6- and p9-dependent virus release.
Synonyms: Vps46-2; hVps46-2; C18orf2; CHMP1.5; Vps46B; C10orf2; C18-ORF2
Tractability: Antibody: UniProt places it where antibodies can reach, with high confidence; its Gene Ontology location is reachable by antibodies, with high confidence. PROTAC: ubiquitination databases record sites on it; its protein half-life has been measured.
Gene: Protein-coding gene on chromosome 18 (11,851,413 to 11,854,444, forward strand). Ensembl gene ENSG00000255112.
Subcellular location: Cytoplasm, cytosol; Endosome; Late endosome membrane
Subcellular location (Human Protein Atlas): Midbody; Nucleoplasm
Gene Ontology:
Molecular function: identical protein binding; MIT domain binding; protein binding; protein domain specific binding
Biological process: autophagosome maturation; autophagy; cell division; establishment of protein localization; late endosome to lysosome transport; midbody abscission; mitotic metaphase chromosome alignment; multivesicular body sorting pathway; nuclear membrane reassembly; nucleus organization; plasma membrane repair; regulation of centrosome duplication; regulation of mitotic spindle assembly; ubiquitin-dependent protein catabolic process via the multivesicular body sorting pathway; viral budding from plasma membrane; viral budding via host ESCRT complex; ESCRT III complex disassembly; late endosome to vacuole transport; membrane fission; multivesicular body assembly; multivesicular body-lysosome fusion; vesicle fusion with vacuole; vacuolar transport
Cellular component: amphisome membrane; autophagosome membrane; endosome membrane; ESCRT III complex; extracellular exosome; kinetochore; kinetochore microtubule; lysosomal membrane; membrane coat; midbody; multivesicular body membrane; nuclear pore; plasma membrane; cytosol; endosome; late endosome membrane
Genetic constraint (gnomAD): Loss-of-function variants: 5 observed, 12.1 expected, observed/expected ratio (o/e) 0.41, 90% interval 0.22 to 0.87. The upper end of that interval is the gene's LOEUF score, 0.87, which puts it in group 3 of 6, group 1 being the genes least tolerant of losing a copy. Missense variants: 246 observed, 273.71 expected, observed/expected ratio (o/e) 0.9, 90% interval 0.81 to 1. Synonymous variants: 105 observed, 114.48 expected, observed/expected ratio (o/e) 0.92, 90% interval 0.78 to 1.08.
Homologues: Orthologues: mouse Chmp1b (98% identical), rat Chmp1b (98% identical), rabbit CHMP1B (94% identical), zebrafish chmp1b (89% identical), tropical clawed frog chmp1b (86% identical), Drosophila melanogaster Chmp1 (73% identical), Caenorhabditis elegans did-2 (57% identical). Paralogues in human: CHMP1A (55% identical), CHMP2A (29% identical), CHMP3 (21% identical), CHMP2B (18% identical).
Diseases named in the same sentence as CHMP1B in open-access papers:
CHMP1B is named in the same sentence as 7 diseases in open-access papers, as found by Europe PMC text mining. Sharing a sentence is not in itself a finding about the gene and the disease. The quoted sentences say what the papers report.
hereditary spastic paraplegia (2 papers, 2017 to 2025). Hereditary spastic paraplegias (HSP) comprise a genetically and clinically heterogeneous group of neurodegenerative disorders characterized by progressive spasticity and hyperreflexia of the lower limbs. "One of them, linked to hereditary spastic paraplegia, is the CHMP1B retrogene encoding chromatin-modifying protein 1B." (PMID 28406439, 2017). "In this regard, Parkinson’s Disease is commonly associated with endolysosomal trafficking phenotypes, while CHMP2B and CHMP1B, whose homologues both play roles in Rab11-exosome and DCG biogenesis in fly SCs, are linked to frontotemporal dementia and hereditary spastic paraplegia respectively." (PMID 40676215, 2025).
glioma (1 paper, 2021). A benign or malignant brain and spinal cord tumor that arises from glial cells (astrocytes, oligodendrocytes, ependymal cells). "For instance, MVB12A, VPS25, CHMP2A, and IST1 were significantly upregulated in glioma, whereas VPS36 and CHMP1B were significantly downregulated." (PMID 34863175, 2021).
Pancreatic Cancer (1 paper, 2022). "In current study, we found the two commonly identified proteins, CHMP1A and CHMP1B, were tumor-associated proteins in the Pancreatic Cancer Database." (PMID 36266629, 2022).
tumor (3 papers, 2022 to 2025). "In the case of DCs, the NPA gene, CHMP1B was up-regulated in tumor tissues, while PARP1 was down-regulated in tumor samples." (PMID 38149248, 2023).
CHMP1B also shares sentences with these, for which no sentence is quoted: infection (2 papers); frontotemporal dementia (1); Parkinson disease (1).